BDNF (brain derived neurotrophic factor)
Diseases named in the same sentence as BDNF in open-access papers (continued):
Sharing a sentence is not in itself a finding about the gene and the disease.
Alzheimer disease (continued). "In the context of our study, the applied differentiation protocol, using a combination of RA and BDNF over 12 days, yielded a cholinergic neuronal model particularly useful for Alzheimer’s disease (AD)." (PMID 38941065, 2025). "Brain‐derived neurotrophic factor (BDNF) and secreted amyloid precursor protein‐alpha (sAPPα) promote neuronal growth but are lower in people with Alzheimer's Disease (AD)." (PMID 40405549, 2025). "BDNF is essential for synaptic plasticity to improve motor functions such as learning and memory in Alzheimer’s disease (AD) and Parkinson’s disease (PD)." (PMID 39754647, 2025). "This study expands upon previous work investigating behavioral alterations in mice with Alzheimer’s disease and a potential treatment of increasing brain-derived neurotrophic factor (BDNF) using repetitive transcranial magnetic stimulation (rTMS)." (PMID 39766385, 2024). "Levels of BDNF were found to decrease in subjects with age-related cognitive decline and Alzheimer’s disease." (PMID 39211673, 2024). "Studies have also shown that an increase in BDNF levels in Alzheimer’s disease leads to a reduction in the production of toxic Aβ through alpha-secretase processing of APP, as well as inhibition of tau phosphorylation." (PMID 39596443, 2024). "A breadth of literature has established the link between lower BDNF levels in individuals diagnosed with neurodegenerative disorders such as Huntington’s disease (HD), Alzheimer’s disease (AD), and multiple sclerosis (MS)." (PMID 39696694, 2024). "For example, the administration of MSCs in mice with Alzheimer’s disease led to increased levels of BDNF and IL-10, which correlated with improved cognitive function and decreased neuroinflammation." (PMID 39596443, 2024). "Investigations suggest that deficits in BDNF signaling contribute to the pathogenesis of several major diseases and disorders, such as Huntington’s disease, Alzheimer’s disease, and depression." (PMID 39061398, 2024). "Studies on individuals with Alzheimer’s disease have shown low plasma concentrations of BDNF, and post-mortem analysis of hippocampal samples has revealed reduced BDNF expression." (PMID 39337980, 2024). "Alterations in BDNF and NGF levels have been associated with Alzheimer's disease, psychiatric disorders, and other neurodegenerative diseases." (PMID 39628974, 2024). "Conclusively, in the present review, we discuss the myelin pathophysiology in Alzheimer's Diseases, as well as the role of neurotrophins, and specifically BDNF, in myelin maintenance and restoration, revealing its valuable therapeutic potential against AD." (PMID 39285941, 2024). "Brain-derived neurotrophic factor (BDNF) is a type of neurotrophin that plays a key part in cognitive function and also in the pathology of Alzheimer’s disease and Huntington’s disease." (PMID 38333757, 2024). "Irisin mediated a protective effect on Alzheimer's disease and Parkinson's disease by inhibiting neuroinflammation, regulating brain-derived neurotrophic factor, and synaptic plasticity." (PMID 39698584, 2024). "Specifically, this polymorphism has been linked to amnestic mild cognitive impairment and its advancement to Alzheimer’s disease, attributed to increased methylation of the BDNF promoter." (PMID 39935805, 2024). "Alternation of BDNF is observed in the pathophysiological basis of many neurodegenerative and psychiatric disorders, including Alzheimer’s disease and depression." (PMID 38648255, 2024). "BDNF secreted by NSCs was shown to correct cognitive deficit in Alzheimer’s disease and radiation injury models." (PMID 39329707, 2024). "A recent meta-analysis showed that serum BDNF was lower in those with Alzheimer’s disease compared to healthy controls." (PMID 38790190, 2024). "Overexpression of BDNF improves cognitive function and ameliorates impairment of synaptic plasticity in mice with Alzheimer’s disease." (PMID 38783169, 2024).
Alzheimer disease (continued). "Enhancing BDNF pharmacologically has shown potential in ameliorating Alzheimer’s disease pathology and memory impairment, emphasizing BDNF’s essential role in adult hippocampal neurogenesis and cognitive function maintenance." (PMID 38667284, 2024). "Hock C., Heese K., Hulette C., Rosenberg C., Otten U. Region-specificneurotrophin imbalances in Alzheimer disease: decreased levelsof brain-derived neurotrophic factor and increased levels of nervegrowth factor in hippocampus and cortical areas." (PMID 39027123, 2024). "Pathways of calcium regulation, G protein signaling, Alzheimer’s disease signaling, and BDNF signaling were upregulated in all four cell types." (PMID 38442272, 2024). "Serum levels of BDNF are lower in patients with Alzheimer's disease than in control subjects and increase when treated with an acetylcholinesterase inhibitor." (PMID 39568824, 2024). "Another study investigated the use of GLUT1 to transport brain‐derived neurotrophic factor (BDNF) into the brain as a potential treatment for Alzheimer's disease." (PMID 38059686, 2024). "Reduced levels of brain-derived neurotrophic factor (BDNF), which is important for synaptic development and plasticity, have also been noted in PD, schizophrenia, and Alzheimer’s disease." (PMID 39408813, 2024). "The therapeutic benefit of NGF and BDNF has been tested in many neurodegenerative diseases treatment, including Alzheimer's disease." (PMID 39285941, 2024). "Conversely, reductions in estrogen and BDNF levels have been reported in patients with Parkinson's disease, Alzheimer's disease (AD), postmenopausal women, ovariectomized (OVX) mouse models, and ER-deficient mouse models." (PMID 39655343, 2024). "P021 was shown to ameliorate learning and memory deficits in animal models of aging and Alzheimer’s disease (AD), and to rescue cognitive impairment in rodent models of DS and AD by enhancing transcription and expression of BDNF." (PMID 39592934, 2024). "Reduced BDNF levels and signaling are linked to neurodegenerative diseases such as MCI, Alzheimer’s Disease (AD), and Parkinson’s Disease (PD)." (PMID 39876995, 2024). "The expression levels of BDNF and its receptor and signaling are also important in the development and progression of Alzheimer’s disease (AD)." (PMID 38827289, 2024). "In the present review we discuss the complex interplay between BDNF signaling impairment, myelin disruption, and the progression of Alzheimer's disease, as well as the therapeutic potential of BDNF targeting in establishing a re-myelination approach in AD." (PMID 39285941, 2024). "The exercise-induced growth factor BDNF also plays a crucial role in neuronal survival, promoting regeneration in injured brains and resistance to degenerative disorders such as Alzheimer’s disease via the PI3K/Akt signaling axis." (PMID 37047523, 2023). "Reduced BDNF expression has been demonstrated in patients with Alzheimer’s disease in the hippocampus, dentate gyrus, new cortex, and nucleus basalis of Meynert." (PMID 37958943, 2023). "Physical activity has been shown to increase plasma brain-derived neurotrophic factor (BDNF), which is thought to reduce amyloid-beta toxicity linked to Alzheimer's disease progression." (PMID 36756008, 2023). "A separate meta-analysis of fifteen studies found that Alzheimer’s disease (AD) patients had decreased levels of serum BDNF compared to healthy controls." (PMID 37763230, 2023). "The results show that Alzheimer disease reduces the concentrations of BDNF and FRAP while increasing the concentration of MDA." (PMID 39484298, 2023). "In the last decade, increasing evidence has emerged linking alterations in the brain-derived neurotrophic factor (BDNF) expression with the development of Alzheimer’s disease (AD)." (PMID 36979505, 2023). "In the APP/PS1 mouse model of Alzheimer’s disease, Aβ decreases brain BDNF expression, but BDNF treatment inhibits Aβ deposition and ameliorates cognitive decline." (PMID 37760929, 2023).
Alzheimer disease (continued). "Quercetin has also been shown to increase the proliferation of hippocampal neurons by enhancing the levels of CREB (cAMP response element-binding protein) and BDNF (brain-derived neurotrophic factor) in the brains of rats with induced Alzheimer’s disease." (PMID 38068936, 2023). "Study on brain-derived neurotrophic factor and oxidative stress roles in Alzheimer’s disease by year order." (PMID 38053647, 2023). "Disturbances in the synthesis, processing, or transport of BDNF can lead to various neurological diseases and mental disorders, including Alzheimer’s disease, Huntington’s chorea, Rett syndrome, schizophrenia, depression, epilepsy, etc.." (PMID 38203674, 2023). "Acute aerobic exercise increased the BDNF plasma levels in patients with Alzheimer’s disease and healthy controls." (PMID 37371860, 2023). "Modification of BDNF levels in serum has been described in epilepsy, psychiatric disorders, neurodegenerative diseases including Alzheimer’s disease, and schizophrenia." (PMID 37109038, 2023). "BDNF signaling plays a role in the pathogenesis of several important diseases, including Alzheimer’s disease (AD), depression, schizophrenia, and anxiety disorders." (PMID 37108295, 2023). "Nonetheless, several reports have linked irisin to improvements in cognitive function, including in individuals with Alzheimer's disease (AD), possibly involving BDNF signaling." (PMID 37268247, 2023). "Beyond Alzheimer’s disease, impairment of BDNF/TrkB signaling is also likely to play a role and other conditions." (PMID 37470055, 2023). "A separate study successfully replicated the beneficial effects of exercise on mice with Alzheimer’s disease by genetically and pharmacologically inducing adult hippocampal neurogenesis and increasing BDNF levels in mice." (PMID 37507961, 2023). "Here, we review recent literature on the mechanisms behind exercise-induced BDNF upregulation and its effects on improving learning and memory and on Alzheimer's disease pathology." (PMID 38002258, 2023). "For example, elevated BDNF levels have been found in patients with early-stage Alzheimer’s disease, probably as a compensatory mechanism to combat early neurodegeneration or to activate immune cells." (PMID 38137853, 2023). "The results are in agreement with previous studies on the relation between Alzheimer’s disease and the concentration of BDNF." (PMID 39484298, 2023). "In animal models of Alzheimer's disease, flavonoids reduce amyloid-beta protein oligomerization and modulate the brain-derived neurotrophic factor (BDNF) signaling pathway." (PMID 37396132, 2023). "In humans, reduced BDNF mRNA expression has been observed during post-mortem examination of patients with Alzheimer’s disease." (PMID 37927591, 2023). "Liao J., Chen C., Ahn E.H., Liu X., Li H., Edgington-Mitchell L.E.,Lu Z., Ming S., Ye K. Targeting both BDNF/TrkB pathway and delta-secretase for treating Alzheimer’s disease." (PMID 37465194, 2023). "This association was modified by allelic variants in genes ABCA7, CLU, BDNF and MS4A6A that have been previously linked to Alzheimer’s disease." (PMID 37658429, 2023). "The aim of this study was to investigate the possible association of levels of BDNF and COMT gene expression and methylation in peripheral blood cells with the development of Alzheimer’s disease (AD)." (PMID 36830773, 2023). "Accordingly, the BDNF level was also significantly upregulated in the scopolamine-induced Alzheimer’s disease (AD) model of adult mouse brains following the TASE and thymol treatments in our previous report." (PMID 37239909, 2023). "It was also found that BDNF improved cell signal transduction and restored learning and memory through amyloid‐independent mechanisms in rodent and primate models of Alzheimer's disease." (PMID 35274832, 2022). "Overexpression of CBP in the hippocampus increases the expression of BDNF and ameliorates spatial memory deficits in Alzheimer's disease (AD) mouse model." (PMID 35992599, 2022).
Alzheimer disease (continued). "Piperine was found to enhance BDNF in animal models of aging, depression, Alzheimer’s disease, PD, stroke, brain ischemia and showed neuroprotection." (PMID 36438833, 2022). "In an Alzheimer’s disease model, blocking BDNF/TrkB neurotrophic signaling up-regulated inflammatory factors and activated the JAK2/STAT3 pathway, therefore up-regulating CEBPB." (PMID 35204186, 2022). "It is well established that dysfunction of BDNF has been involved in the progression of multiple neurological diseases and psychiatric disorders such as Alzheimer’s disease, stroke, and depression." (PMID 36329115, 2022). "The modification of BDNF and/or the expression of its receptors (TrkB.FL, TrkB.T1 and TrkB.T2) have been described during normal aging and in Alzheimer’s disease." (PMID 35625880, 2022). "Strikingly, in rodent and primate models of Alzheimer’s disease, BDNF gene delivery administered after disease onset showed potent neuroprotective effects by increasing synaptogenesis and synaptic plasticity leading to restoration of cognitive function." (PMID 36397124, 2022). "On the other hand, augmenting BDNF transmission rescues plasticity impairments in certain brain regions in murine models of Alzheimer’s disease, Huntington’s disease, fragile X syndrome, chronic intermittent hypoxia, schizophrenia, and aging." (PMID 35955546, 2022). "Previous studies also show that BDNF expression is reduced in the cortex of Alzheimer's disease patients." (PMID 35308288, 2022). "Certainly, ten years after diagnosis for dementia, levels of serum BDNF were found that were initially observed at the treatment stages of Alzheimer’s disease." (PMID 35625880, 2022). "A systematic review and meta-analysis conducted in 2019 found that patients with Alzheimer’s disease have lower levels of BDNF, especially during the late stages of the disease." (PMID 35625880, 2022). "This method has been tested in the treatment of Alzheimer’s disease, using adenovirus as a viral vector to deliver BDNF gene into the nucleus basalis." (PMID 35625880, 2022). "For instance, curcumin induced the mRNA and protein level of JMJD3 in human neuroblastoma cells with consequent decrease in H3K27me3 at the BDNF promoter region and increase in BDNF expression, suggesting a protective role of curcumin in Alzheimer's disease." (PMID 36300880, 2022). "Dysregulated brain-derived neurotrophic factor (BDNF)/tropomyosin receptor kinase B (TrkB) signalling is implicated in several neurodegenerative diseases, including Alzheimer’s disease." (PMID 36555849, 2022). "Altered levels of BDNF have been reported in a number of neurodegenerative diseases, including stroke, Parkinson’s disease, and Alzheimer’s disease." (PMID 35887140, 2022). "CRF protects neurons in the amygdala and hippocampus against Alzheimer’s disease-related degeneration, probably via enhancements of brain-derived neurotrophic factor (BDNF) signaling pathways and Aβ clearance." (PMID 35326315, 2022). "The present study conducted a screening of potent abrineurin/BDNF natural inducers to find multi-targeting agents against Alzheimer’s Disease." (PMID 35626478, 2022). "In this context, promising results have been found with BDNF which, by activating the TrkB receptor, can protect neurons from death in, for example, preclinical models of PD, Alzheimer’s disease (AD), and ischemic lesions." (PMID 35890231, 2022). "CREB and BDNF levels are low in the brains of patients affected by Alzheimer’s disease or other neurodegenerative diseases." (PMID 35615594, 2022). "Brain-derived neurotrophic factor (BDNF) is known to be involved in thepathogenesis of Alzheimer’s disease (AD)." (PMID 36694902, 2022). "Recent evidence showed that physical exercise protects the brain from Alzheimer’s disease (AD) memory impairment through increasing hippocampal neurogenesis in a necessary combination with BDNF." (PMID 35740319, 2022).
Alzheimer disease (continued). "MD also influences brain-derived neurotrophic factor (BDNF) production, whose alterations contribute to the etiopathogenesis of Alzheimer’s disease (AD)." (PMID 36613538, 2022). "An in vitro Alzheimer’s disease model study suggested that cocoa exerted its neuroprotective effects through activating BDNF signaling pathway." (PMID 34329196, 2021). "For example, hexadecanamide has been reported to upregulate hippocampal BDNF expression and improve cognitive functions in a mouse model of Alzheimer’s disease." (PMID 34977362, 2021). "Increased passage of MSCs naturally boost secretion of BDNF; MSCs are promising delivery systems for therapeutics in various neurodegenerative disorders, such as Alzheimer’s disease and Parkinson’s disease, because of their secretomes." (PMID 34690674, 2021). "Our SNPs can also interact in a synergistic manner to create the observed BDNF expression changes, as which occurs in Alzheimer’s disease." (PMID 33757426, 2021). "Recent work has shown that a high fat diet (HFD) leads to reduced BDNF protein content and impaired BDNF signaling that is similar to what is observed with Alzheimer’s disease." (PMID 34017238, 2021). "Other studies have shown that PBM rescues dendritic atrophy in Alzheimer’s disease by upregulating brain-derived neurotrophic factor (BDNF)." (PMID 34359834, 2021). "Stimulation of BDNF signaling by EE in the hippocampus of mice Alzheimer’s disease model has also been observed by up-regulating BDNF mRNA expression level." (PMID 33503967, 2021). "Our findings exhibit comparable implications, specifically in a pre-clinical sporadic model of Alzheimers disease, while also elucidating a potential mechanism behind the neuroprotective effects of BDNF." (PMID 34017238, 2021). "7,8-Dihydroxyflavone, which is an agonist of tropomyosin-related kinase B (TrkB), a BDNF and neurotrphin-4/5 (NT-4/5) receptor, also has similar beneficial effects on Alzheimer’s disease model mice." (PMID 34977362, 2021). "Dysregulation of BDNF and its main receptor, TrkB, has been documented in neurodegenerative disorders such as Parkinson's disease, Alzheimer's disease, and psychiatric diseases." (PMID 35496352, 2021). "Recently, the promising functions of BDNF in Alzheimer's disease (AD) have been reported; however, the role of BDNF in PD is still unclear." (PMID 34132500, 2021). "Social interaction has also been shown to rescue memory impairment in an Alzheimer’s disease mouse model through a hippocampal BDNF-mediated pathway." (PMID 34299756, 2021). "Clinical evidence and in vivo models have demonstrated that there is a reduction in expression and protein content of BDNF in Alzheimer’s disease transgenic mice and post-mortem brains of patients with Alzheimer’s disease." (PMID 34017238, 2021). "We also report that simultaneous overexpression of BDNF and TrkB enhances axonal transport in two neurodegenerative disease models: a humanized tauopathy model of Alzheimer’s disease and an experimental glaucoma model." (PMID 33789891, 2021). "Reduced estrogen and BDNF levels were reported in patients with Parkinson’s disease and Alzheimer’s disease." (PMID 33953866, 2021). "Several lines of evidence indicate BDNF levels play an important role in the pathogenesis of several neurodegenerative diseases, including Alzheimer’s disease (AD)." (PMID 33801925, 2021). "Reduced levels of BDNF have been described as being involved in the pathogenesis of Alzheimer disease." (PMID 33643008, 2021). "A number of studies have demonstrated the possible involvement of altered expression and action of the BDNF/TrkB signaling in the pathogenesis of neurodegenerative diseases, including Alzheimer’s disease (AD)." (PMID 34071978, 2021). "In neuronal culture, elevating the levels of FNDC5 was found to reverse the apoptotic effects of Ab1−42 oligomers in Alzheimer's disease (AD) model and counteracts the suppression of BDNF expression by them." (PMID 34018309, 2021).